CPSF3 (cleavage and polyadenylation specific factor 3)
Description:
Component of the cleavage and polyadenylation specificity factor (CPSF) complex that plays a key role in pre-mRNA 3'-end formation, recognizing the AAUAAA signal sequence and interacting with poly(A) polymerase and other factors to bring about cleavage and poly(A) addition. Has endonuclease activity, and functions as an mRNA 3'-end-processing endonuclease. Also involved in the histone 3'-end pre-mRNA processing. U7 snRNP-dependent protein that induces both the 3'-endoribonucleolytic cleavage of histone pre-mRNAs and acts as a 5' to 3' exonuclease for degrading the subsequent downstream cleavage product (DCP) of mature histone mRNAs. Cleavage occurs after the 5'-ACCCA-3' sequence in the histone pre-mRNA leaving a 3'hydroxyl group on the upstream fragment containing the stem loop (SL) and 5' phosphate on the downstream cleavage product (DCP) starting with CU nucleotides. The U7-dependent 5' to 3' exonuclease activity is processive and degrades the DCP RNA substrate even after complete removal of the U7-binding site. Binds to the downstream cleavage product (DCP) of histone pre-mRNAs and the cleaved DCP RNA substrate in a U7 snRNP dependent manner. Required for entering/progressing through S-phase of the cell cycle. Required for the selective processing of microRNAs (miRNAs) during embryonic stem cell differentiation via its interaction with ISY1 (By similarity). Required for the biogenesis of all miRNAs from the pri-miR-17-92 primary transcript except miR-92a (By similarity). Only required for the biogenesis of miR-290 and miR-96 from the pri-miR-290-295 and pri-miR-96-183 primary transcripts, respectively (By similarity).
Synonyms: CPSF73; CPSF-73; YSH1; NEDMHS; NEDMHSN
Tractability: Small molecule: a structure with a bound ligand is known; it has a high-quality binding pocket. PROTAC: UniProt records ubiquitination sites on it; ubiquitination databases record sites on it; its protein half-life has been measured.
Target class: Enzyme; Hydrolase
Gene: Protein-coding gene on chromosome 2 (9,423,631 to 9,473,110, forward strand). Ensembl gene ENSG00000119203.
Subcellular location: Nucleus
Pathways (Reactome):
Metabolism of RNA: Processing of Intronless Pre-mRNAs; Transport of Mature mRNA Derived from an Intronless Transcript; mRNA 3'-end processing; mRNA Polyadenylation
Disease: Dengue Virus-Host Interactions
Gene expression (Transcription): RNA Polymerase II Transcription Termination
Gene Ontology:
Molecular function: metal ion binding; protein binding; RNA endonuclease activity; 5'-3' RNA exonuclease activity; RNA binding
Biological process: co-transcriptional mRNA 3'-end processing, cleavage and polyadenylation pathway; mRNA 3'-end processing; mRNA 3'-end processing by stem-loop binding and cleavage; positive regulation of G1/S transition of mitotic cell cycle; nuclear histone mRNA catabolic process
Cellular component: mRNA cleavage and polyadenylation specificity factor complex; nucleus; mRNA cleavage factor complex; nucleoplasm
Genetic constraint (gnomAD): Loss-of-function variants: 37 observed, 48.21 expected, observed/expected ratio (o/e) 0.77, 90% interval 0.59 to 1.01. The upper end of that interval is the gene's LOEUF score, 1.01, which puts it in group 4 of 6, group 1 being the genes least tolerant of losing a copy. Missense variants: 318 observed, 547.13 expected, observed/expected ratio (o/e) 0.58, 90% interval 0.53 to 0.64. Synonymous variants: 173 observed, 184.83 expected, observed/expected ratio (o/e) 0.94, 90% interval 0.83 to 1.06.
Homologues: Orthologues: chimpanzee CPSF3 (99% identical), macaque CPSF3 (99% identical), dog CPSF3 (99% identical), pig CPSF3 (99% identical), mouse Cpsf3 (98% identical), rat Cpsf3 (98% identical), guinea pig CPSF3 (97% identical), rabbit CPSF3 (95% identical), tropical clawed frog cpsf3 (89% identical), zebrafish cpsf3 (88% identical), Drosophila melanogaster Cpsf73 (66% identical), Caenorhabditis elegans cpsf-3 (55% identical). Paralogues in human: INTS11 (32% identical), CPSF2 (21% identical), INTS9 (18% identical).
Diseases named in the same sentence as CPSF3 in open-access papers:
CPSF3 is named in the same sentence as 31 diseases in open-access papers, as found by Europe PMC text mining. Sharing a sentence is not in itself a finding about the gene and the disease. The quoted sentences say what the papers report.
Ewing sarcoma (6 papers, 2020 to 2025). A small round cell tumor that lacks morphologic, immunohistochemical, and electron microscopic evidence of neuroectodermal differentiation. "JTE-607-mediated inhibition of CPSF3 led to alterations in the expression of known downstream effectors in both acute myeloid leukemia and Ewing’s Sarcoma." (PMID 38503731, 2024). "Preclinical efficacy for molecules targeting the cleavage and polyadenylation complex component CPSF3 has shown efficacy in leukemia, Ewing’s sarcoma, ovarian, and pancreatic cancer models." (PMID 39316554, 2024). "Therefore, we propose that CPSF3 regulates cell proliferation through distinct mechanisms in AML and Ewing's sarcoma relative to PDAC." (PMID 38191171, 2024).
colorectal cancer (4 papers, 2019 to 2025). A primary or metastatic malignant neoplasm that affects the colon or rectum. "CPSF3 (Polyadenylation specificity factor 3) protein interacts with a lncRNA CASC9 (Cancer Susceptibility 9), and knockdown of CPSF3 mimicked the effects of CASC9 knockdown in colorectal cancer cells." (PMID 37042179, 2023). "Notably, SRSF3, CPSF3, FIP1L1, CTR9, NUDT21, and CSTF2, among others, were found to exhibit a more significant contribution to the differential 3′-UTR gene expression in colorectal cancer." (PMID 40702779, 2025). "While in colorectal cancer, CASC9 interacted with CPSF3 to regulate TGF-β signal transduction." (PMID 36248984, 2022).
ovarian carcinoma (4 papers, 2018 to 2024). A malignant neoplasm originating from the surface ovarian epithelium. "As an important component of APA, CPSF is usually upregulated in cancers, such as CPSF1 in HCC and ovarian cancer, CPSF3 in HCC, CPSF4 in colorectal and lung cancers, and CPSF7 in HCC." (PMID 36349192, 2022). "Importantly, these CPSF factors lead to the growth of human cancer, such as breast, ovarian cancer, and even the inhibition of CPSF3 actuates apoptosis in prostate cancer cells." (PMID 33692831, 2021).
breast carcinoma (3 papers, 2024 to 2025). "Surprisingly, two separate studies have revealed that UBE3D can stabilize CPSF3 (cleavage and polyadenylation specific factor 3) in 3T3-L1 cells and breast cancer cells." (PMID 40075082, 2025).
colon cancer (2 papers, 2020 to 2023). "NUDT21, CPSF3, CSTF2, and MTPAP were overexpressed while PCF11 and PABPN1 were suppressed in colon cancer tissues." (PMID 32153636, 2020).
glioma (2 papers, 2024 to 2025). A benign or malignant brain and spinal cord tumor that arises from glial cells (astrocytes, oligodendrocytes, ependymal cells). "We then performed in silico analysis to confirm that high RBBP6 and CPSF3 expression correlated with worse survival in glioma patients." (PMID 38503731, 2024).
Intellectual disability (2 papers, 2022 to 2024). "Recently, homozygosity in CPSF3 missense variants was found to cause intellectual disability and embryonic lethality in humans." (PMID 38191171, 2024). "In total, we have identified six patients who are homozygous for missense variants in CPSF3, as well as two suspected homozygous carriers, all of whom present with features of intellectual disability, seizures, microcephaly, and abnormal muscle tone." (PMID 35121750, 2022). "However, the phenotypes of patients E and F, including intellectual disability, motor delay, and microcephaly, strongly suggests they have the same condition as the genotypically confirmed CPSF3 p.Gly468Glu homozygous patients." (PMID 35121750, 2022).
intellectual disability syndrome (2 papers, 2022 to 2025). "Guided by the homozygote deficit, we discovered that missense variants in CPSF3 cause a severe intellectual disability syndrome in homozygous carriers." (PMID 35121750, 2022). "Furthermore, homozygous missense variants in CPSF3 show severe symptoms of intellectual disability syndrome, while heterozygous carriers of the same variant lack these symptoms." (PMID 41463412, 2025).
pancreatic cancer (2 papers, 2024). "In conclusion, our study has revealed the role of CPSF3 in pancreatic cancer and uncovered a new mechanism by which CPSF3 regulates cell proliferation." (PMID 38191171, 2024).
toxoplasmosis (2 papers, 2017 to 2018). A parasitic disease contracted by the ingestion or fetal transmission of toxoplasma gondii. "CPSF3, an essential component for converting heteronuclear RNA to mRNA, is associated with cellular stress response 1 protein-mediated cell death and also can be designed as an novel target for control toxoplasmosis." (PMID 30052469, 2018). "Knock‐in of the mutations using CRISPR/Cas9 gene editing recapitulated the phenotype resistance to AN3661 both in vitro and in the murine model of toxoplasmosis, thus validating CPSF3 as the primary target of AN3661." (PMID 28148555, 2017).
African trypanosomiasis (1 paper, 2022). "During the course of this work, several benzoxaborole analogues of AN15368 with efficacy in the treatment of African trypanosomiasis in cattle were shown to target the Cleavage and Polyadenylation Specificity Factor (CPSF3), an important factor in messenger RNA processing." (PMID 36065062, 2022).
asthma (1 paper, 2022). "The rs12151757 in CPSF3 showed the highest statistical association (P = 9.46 × 10–6) with asthma and this SNP acts as an eQTL of ADAM17." (PMID 35130903, 2022).
bladder cancer (1 paper, 2024). "CPSF3 plays an important role in inducing cell death and is associated with patient prognosis and cancer recurrence in multiple cancers, including bladder cancer and LUAD." (PMID 38213773, 2024).
Cirrhosis (1 paper, 2023). A chronic disorder of the liver in which liver tissue becomes scarred and is partially replaced by regenerative nodules and fibrotic tissue resulting in loss of liver function. "However, due to the limited sample size of tissue microarray data, we were unable to determine whether hepatic background CPSF3 expression was associated with a specific etiology such as cirrhosis." (PMID 37627085, 2023).
glioblastoma (1 paper, 2024). The most malignant astrocytic tumor (WHO grade IV). "Collectively, these results demonstrated that RBBP6 and CPSF3 are potential therapeutic targets in glioblastoma." (PMID 38503731, 2024). "Our data suggest that approaches to modulate APA in GSCs by targeting RBBP6 or CPSF3 showed high therapeutic efficacy, offering novel strategies for glioblastoma treatment." (PMID 38503731, 2024). "In summary, by utilizing an in vitro and in vivo CRISPR screening, we identified the dependency on the RBBP6/CPSF3-APA-MYC axis in glioblastoma." (PMID 38503731, 2024). "Our identification of the dependency on the RBBP6/CPSF3-APA-MYC axis in glioblastoma offers novel strategies for lethal cancers." (PMID 38503731, 2024). "Collectively, RBBP6 maintains high MYC expression in GSCs through regulation of CPSF3-dependent alternative polyadenylation, providing a potential therapeutic paradigm for glioblastoma." (PMID 38503731, 2024).
liver cancer (1 paper, 2024). An epithelial or non-epithelial malignant neoplasm that arises from the liver. "This is consistent with similar findings across the cancer landscape, where CPSF3 has been reported to be a predictor of unfavorable prognosis in lung and liver cancers." (PMID 38191171, 2024).
cancer (14 papers, 2018 to 2025). A tumor composed of atypical neoplastic, often pleomorphic cells that invade other tissues. "While several studies have experimentally manipulated various mRNA processing factors and determined the phenotypic impacts, little is known about the function of CPSF3 in disease, particularly cancer." (PMID 38191171, 2024). "This property, coupled with our data demonstrating JTE-607's antiproliferative effects on cancer cells, supports the contention that targeting CPSF3 is a feasible prospect in PDAC." (PMID 38191171, 2024). "Overall, our findings uncover new functions of CPSF3 in cancer and nominate CPSF3 as a novel therapeutic target in PDAC." (PMID 38191171, 2024). "Our findings indicate that higher levels of SEC31A1 are positively associated with increased IC50 values of cancer therapy drugs, whereas the expression of TOPBP1, ESPL1, and CPSF3 displayed an opposite correlation." (PMID 37417208, 2023). "Inhibition of CPSF3, and blocking the release of newly synthesized pre-mRNAs, can enforce cellular apoptosis and has been considered as potential cancer treatment." (PMID 35121750, 2022). "Consequently, the CPSF3-mediated APA processing pathway holds promise as a target for cancer treatment." (PMID 38503731, 2024). "Both CPSF3 and NMT are present in eukaryotic cells and are promising targets for prospective HAT drugs as well as the treatment of cancer." (PMID 37569903, 2023). "Since CPSF3 expression is also negatively affected by both PladB and THZ531 treatment, these findings suggest that 22Rv1 cells particularly rely on these two 3’-end processing factors and that their repression could contribute to the anti-cancer activity of splicing-targeting drugs." (PMID 38413979, 2024).
tumor (6 papers, 2018 to 2024). "The univariate analysis showed that the OS of HCC patients was linked to tumor stage, primary tumor size, and high CPSF3 expression (p < 0.001)." (PMID 37627085, 2023). "As CPSF3 appears to be a critical downstream molecule of RBBP6 in GSCs, we investigated the function of CPSF3 in tumor growth in vivo." (PMID 38503731, 2024). "The clinical significance of CPSF3 expression was evaluated in this cohort of 75 patients, and correlation analysis verified that CPSF3 level was significantly correlated with primary tumor factors and clinical stage." (PMID 37627085, 2023). "The results revealed that CPSF3 was highly expressed in 50 out of 75 tumor tissues, moderately expressed in 25 tumor tissues, and minimally expressed in most PT tissues." (PMID 37627085, 2023). "The results of qRT-PCR and immunohistochemical assays showed that CPSF3 was higher in BC tissues and cell lines than that in adjacent non-tumor tissues and normal human ureteral epithelial cell lines (SV-HUC-1), respectively." (PMID 36175880, 2022). "CPSF3 expression was significantly higher in tumor than that in the normal control group (TCGA, P< 0.001; GSE 13,507, P < 0.001; GSE38264, P < 0.01)." (PMID 36175880, 2022). "Next, we sought to determine the requirement for CPSF3 in PDAC tumor growth in vivo." (PMID 38191171, 2024). "While several recent reports have linked CPSF3 loss to defects in tumor cell growth, no study has mechanistically connected CPSF3 to APA dysregulation." (PMID 38191171, 2024). "Through logistic regression, we found T2 vs. T1 in primary tumor (total (N) = 280), the odds ratio in CPSF3 was 2.44 (95% CI: 1.46–4.14, p-Value = 0.0008); in tumor stage, II vs. I (total (N) = 262), the odds ratio in CPSF3 was 2.4 (95% CI: 1.40–4.15, p-value = 0.0015)." (PMID 37627085, 2023). "The results indicated that CPSF3 may be involved in crucial signaling pathways in tumor immune microenvironment in BC." (PMID 36175880, 2022). "Depletion of RBBP6 or CPSF3 resulted in 3’US of the ceRNA of the OG MYC, thereby reducing MYC expression and leading to inhibition of tumor growth." (PMID 38503731, 2024). "CPSF3 expression was significantly higher in PDAC tumors (n = 135), as compared with non-tumor adjacent tissues (n = 18) and normal pancreata (n = 7)." (PMID 38191171, 2024). "To determine the clinical significance of CPSF3 expression in PDAC, we first analyzed gene expression data from the Clinical Proteomic Tumor Analysis Consortium (CPTAC)." (PMID 38191171, 2024). "Targeting CPSF3 with a small molecular inhibitor (JTE-607) reduces GSC viability and inhibits in vivo tumor growth." (PMID 38503731, 2024). "CPSF3 knockdown blocks PDAC cell proliferation and colony formation in vitro and tumor growth in vivo." (PMID 38191171, 2024). "Overall, these data support the requirement for CPSF3 in PDAC cell proliferation and tumor growth." (PMID 38191171, 2024). "In support of this hypothesis, we show that knockdown of CPSF3 blocks PDAC cell proliferation and tumor growth." (PMID 38191171, 2024). "Further analysis was performed by logistic regression to scrutinize the relationship between the CPSF3 level and the clinical pathological parameters of HCC, and the results demonstrated that CPSF3 was significantly related to tumor stage, tumor grade, and primary tumor size." (PMID 37627085, 2023). "In CRC, this cluster has been shown to augment tumor angiogenesis by repressing TSP1 and CTGF, suggesting that CPSF3 may also be involved in these processes." (PMID 31186036, 2019).
infection (4 papers, 2017 to 2025). The state of being infected such as from the introduction of a foreign agent such as serum, vaccine, antigenic substance or organism. "Knockdown efficiency, quantified by RT-qPCR, showed a 51% and 58% reduction in Cpsf3 at day 6 post-infection with shCPSF3#1 and #2, respectively, becoming slightly less efficient during reprogramming." (PMID 34082786, 2021). "Little research has focused on CPSF3, but like CPSF1, it is thought to be involved in mRNA processing and may contribute to the regulation of gene expression in response to diverse pathogenic microorganisms, such as Toxoplasma gondii, Plasmodium falciparum, and Cryptosporidium infection." (PMID 38515745, 2024). "In addition, mice infected with the resistant TgCPSF3E545K line and then treated with AN3661 did not survive to infection, whereas mice infected with wild‐type strain and treated did, thus validating CPSF3 as the Toxoplasma target of AN3661 in vivo." (PMID 28148555, 2017).
adenocarcinoma (1 paper, 2024). A common cancer characterized by the presence of malignant glandular cells. "Therefore, the potential for CPSF3 as a therapeutic target in adenocarcinoma was an open question." (PMID 38191171, 2024).
CPSF3 also shares sentences with these, for which no sentence is quoted: acute myeloid leukemia (4 papers); prostate carcinoma (4); leukemia (2); lung carcinoma (2); triple-negative breast carcinoma (2); viral infection (2); hepatocellular carcinoma (1); keratoconus (1); microcephaly (1); pancreatic adenocarcinoma (1); renal cell cancer (1).